IL1B (interleukin 1 beta)
Diseases named in the same sentence as IL1B in open-access papers (continued):
Sharing a sentence is not in itself a finding about the gene and the disease.
tumor (continued). "We found that IL-1β inhibition decreased tumor burden, tumor cell proliferation, and tumor angiogenesis, while increasing tumor cell apoptosis from both preventive and early therapeutic perspectives." (PMID 35471938, 2022). "Multiple immune–epithelial interactions involving T/NK cells and McDCs with tumor epithelial cells were predicted in i3 cancers (for example, IL1B in McDCs to IL1R2 in i3 tumor cells)." (PMID 35773407, 2022). "Tumor cell–derived IL-1β activates PSCs and establishes an immunosuppressive milieu mediated by M2 macrophages, MDSCs and Th17 cells." (PMID 35493517, 2022). "Activation of MERTKR in TAM promotes tumor progression by inducing the expression of the proinflammatory cytokines, IL-1β, IL-6, and TNF." (PMID 36679900, 2022). "Following antigen presentation, the CD8+ T cells activate the NLRP3 inflammasomes in DCs, promoting IL-1β maturation and thereby contributing to anti-tumor immunity." (PMID 36376979, 2022). "When SUA level is elevated, both in the state of soluble high uric acid and crystalline uric acid, ROS production and IL-1β formation can be increased, resulting in oxidative stress and inflammatory response and thus promoting tumor progression." (PMID 35965512, 2022). "In pancreatic tumors, the secretion of TNF-α and IL-1β by tumor cells promotes CAFs activation and their secretion of TSLP, which favor the generation of DCs with Th2-polarizing capabilities, associated with reduced patient survival." (PMID 36338519, 2022). "Representative multiplex IHC staining revealed a higher number of double-positive CD3+PD-1+ T cells residing in the tumor in the control group compared with the anti–IL-1β–treated CC-LR mice." (PMID 35471938, 2022). "Recently, several studies have reported that chrysin can enhance the anti-tumor response of CTLs by activating APCs or decreasing the levels of IL-1β and IL-6." (PMID 36615387, 2022). "These revealed that in patients with LUAD (a tumor with high KRAS mutation frequency), high KRAS/CCL2/IL1B expression levels portended 93% increased odds of death regardless of smoking status (upper left)." (PMID 35327394, 2022). "Mechanistically, we found that phagocyte-mediated efferocytosis of dying tumor cells in the TME directly activated NLRP3-dependent inflammasome signaling to drive IL-1β secretion." (PMID 36439171, 2022). "CTCs are disseminated tumor cells that can establish metastases and the Ottewell lab discovered that CTCs and bone metastases have high levels of IL-1β and express EMT markers." (PMID 35626710, 2022). "This suggests that this proinflammatory environment promotes necessary pathways that end in tumor progression facilitated by MDSCs, as observed in the higher tumor growth and survival rate of an IL-1β-injected mammary carcinoma mice model." (PMID 35681719, 2022). "Secondary senesced cells also secrete IL-1β and ROS, which can propagate cellular senescence and stimulate aberrant cell proliferation nearby, resulting in formation of a heterogeneous tumour-like cell mass." (PMID 35304872, 2022). "Among these DEGs, 5 genes were down-regulated in tumor group including IL1B, AIM2, IL6, NLRP3, and NLRP6." (PMID 36127654, 2022). "We were able to rescue the pro-tumor effect of NLRP3 signaling with the addition of recombinant IL-1β." (PMID 36439171, 2022). "Our data support the notion that the IL-1β-mediated EMT pathway is promoting tumor growth, in part through facilitating the breakdown of the collagenase-rich interface." (PMID 36423636, 2022). "It has been postulated that IL1β promotes the recruitment of anti-tumour neutrophils to the lung metastatic niche, inhibiting metastasis to this organ." (PMID 36230739, 2022). "With this initial test, thus, it was possible to determine the role of CCL21/IL1β in migration and movement of immune cells towards tumor cells." (PMID 36037155, 2022). "Tumor cells can directly produce IL-1β or can “instruct” cells within TME, such as stromal ones, to secrete it." (PMID 35530309, 2022).
tumor (continued). "In this tumor model, the enhanced anti-tumor effects of IL-1β-treated Th9 cells were indirect and required IL-21 priming of CD8 T cells and natural killer (NK) cells." (PMID 36389679, 2022). "Accordingly, increased levels of IL-1β were measured in the microenvironment of tumour tissues and serum samples." (PMID 36678401, 2022). "Interleukin 1 Beta (IL-1β), a pro-inflammatory cytokine, has an important role in triggering several oncogenic processes in the tumor microenvironment, such as secretion of cyclooxygenases (COXs) and increase in hypoxia-inducible factor 1α (HIF-1α) activity." (PMID 35057010, 2022). "In two separate studies using pancreatic cancer or breast cancer mouse models, neutralization of IL-1β significantly enhanced the anti-tumor activity of anti-PD-1, and was accompanied by increased tumor infiltration of CD8+ T-cells." (PMID 35086565, 2022). "Post efferocytosis, we observed a significant increase in the transcriptional activation of Il1b and Il1r1 as well as a modest change in the mRNA levels of Nlrp3, consistent with our bulk RNA-seq analysis from sorted human tumor-derived CD11b+ cells." (PMID 36439171, 2022). "Previous findings demonstrated a correlation of upregulated IL-1β with neoplasm initiation and development." (PMID 36013233, 2022). "Studies with the use of PTEN KO murine PC model documented that lack of this gene was associated with upregulated inflammatory response (enhanced production of CSF-1 and IL-1β), and an extensive MDSCs tumor infiltration." (PMID 35860573, 2022). "The release of pyroptosis-related molecules IL-1β and IL-18 can induce the infiltration and activation of tumor immune cells, which is helpful to the anti-tumor immune response." (PMID 36186792, 2022). "Consistently, IL-1β conditioning allows a better response of adoptively transferred anti-tumor T-cells." (PMID 35517498, 2022). "In human xenograft models of kidney cancer, IL-1β regulates tumor growth and its invasiveness, mediated by NLRP3 activation." (PMID 36376979, 2022). "They described that the recruitment of myeloid cells such as neutrophils, macrophages, and MDSCs to the tumor microenvironment by tumor cells promotes the secretion of active IL-1β and other proinflammatory mediators such as CCL2, CCL3, and Bv8." (PMID 35681719, 2022). "IL-1β binds to its receptor leading to the activation of macrophages, intratumoral assembly of immunosuppressive myeloid cells, invasiveness, tumor growth, metastasis, and angiogenesis." (PMID 36577761, 2022). "This was mediated by a cytokine gradient from non-tumor to tumor tissue involving among others the cytokines IL-33, IL-4 and IL-1β." (PMID 35663967, 2022). "On the one hand, IL-1β and IL-18 were correlated with tumor growth, invasion, angiogenesis and metastasis." (PMID 35281845, 2022). "The Apte lab systematically studied the role of IL-1α or IL-1β in tumor initiation and progression using several genetically engineered mouse models." (PMID 36074553, 2022). "These patient characteristics demonstrate the applicability of IL-1β inhibition as a potential strategy for prevention or treatment of KM-LUAD in which inflammation is highly involved in tumor development and progression." (PMID 35471938, 2022). "Several IL-1β mutant models have demonstrated resistance to cancer growth and reduced tumor invasion." (PMID 36430487, 2022). "While the membrane-associated IL-1α is mainly immunostimulatory, IL-1β that is secreted into the TME is mainly pro-inflammatory and promotes tumorigenesis, tumor invasiveness, and immunosuppression." (PMID 36074553, 2022). "Among the candidate factors, IL-1α and IL-1β were suggested to have osteoclastogenic activity and were thought to be strong participants in tumor-induced osteoclastogenesis." (PMID 36614130, 2022).
tumor (continued). "The anticancer potential of the spiro-acridine compounds was associated with antiangiogenic action and up-regulation of Th1-type responses, mainly by inducing the increase of TNF-α and IL-1β levels in the tumor microenvironment." (PMID 36324671, 2022). "Next, considering the potential tumor suppressor role of EPHX3 in HNSCC, we examined the association between EPHX3 and CD274, IL1B, IL1A, PDCD1, and PDCD1LG2." (PMID 35401746, 2022). "In the tumor microenvironment, a large number of cytokines and chemokines, such as IL-1β, IL-6, IL-8, and TNFα, can also induce EMT in OSCC." (PMID 35155249, 2022). "The results revealed that in comparison to the normal saline group, the RANKL and IL-1β expression in tumor tissues of nude mice in treatment group AIL decreased significantly, with statistically significant differences." (PMID 36686653, 2022). "Interleukin-17A (IL-17A) is produced by Th17 cells which infiltrate the tumor microenvironment and induces the expression of several inflammatory cytokines including IL-1β, IL-16 and IL-23, leading to variable effects on tumor growth at different stages." (PMID 36135194, 2022). "We subsequently analyzed the influence of the anatomical tumor localization on concentrations of CgA, the NETest, as well as IL-1β, IL-6, IL-8, IL-10, IL-18, and TNF." (PMID 36294509, 2022). "Although Foxp3+ ROR-γt+ cells were also shown to be present in tumors and contribute to tumor immune evasion and autoimmunity control, the role of increased IL-1β in the context of aging and carcinogenesis remains to be investigated." (PMID 35821823, 2022). "Activating caspase-1 can either lead to cell death or tumor growth by upregulating the secretion of pro-inflammatory molecules such as IL-1β, IL-18, and FGF2." (PMID 35883451, 2022). "As in the case of downmodulation by shRNA, expression of CD47 in anti-SIRPγ mAb–treated tumor cells was restored by exposure to IL-1β and GM-CSF." (PMID 35229723, 2022). "The increased NLRP3 and IL1B transcripts correlated with increased biochemical caspase-1 activity in the tumor infiltrating myeloid cells compared to those isolated from PBMC from cancer patients." (PMID 36439171, 2022). "Meanwhile, a tumor-promoting interaction (interleukin 1 beta (IL1β)–interleukin A receptor type 2 (IL1R2)) between cancer cells and macrophages is also suppressed in METTL1-knockout mice." (PMID 35590385, 2022). "As the IL-1β free environment allows tumor cells to escape maternal immune control, these cells undergo camouflage through an increase in the expression of a selected repertoire of proteins that includes check point proteins such as PDL1; HLAG and βhCG." (PMID 35203462, 2022). "Blockade of IL-1β in a mouse model of PDAC improved tumor-infiltrating lymphocyte (TIL) numbers and CD8+ T-cell responses, which inhibit tumorigenesis." (PMID 36077772, 2022). "C/EBP-homologous protein (CHOP), which is overexpressed in tumor cells, can regulate pro-inflammatory cytokines, such as IL-23, IL-1β, and IL-6, and modulate the activity and survival of tumor cells by inhibiting the immune response of T cells." (PMID 35327508, 2022). "The effective anti‐tumor immune response of 5-FU chemo-immunotherapy was dependent on CD8+ T cells but was unaffected when TNFα or IL-1β cytokine signaling pathways were blocked." (PMID 35634282, 2022). "A pre-clinical study indicated the anti-tumor effects of anti-IL-1β antibody and enhanced response of anti-PD-1 antibody." (PMID 35739593, 2022). "The increased secretion of IL-1β will lead to the production and maintenance of an inflammatory microenvironment surrounding cancer cells, which is conducive to tumor." (PMID 36295848, 2022). "Here, invasion of a collagen-rich matrix was induced by tumor cells via the IL-1β/CEBPβ/MMP pathway." (PMID 36423636, 2022). "They find a more invasive phenotype at the interface separating tumor with normal kidney, which appears to be driven by IL-1β signaling in macrophages." (PMID 36423636, 2022).
tumor (continued). "IL-1β is abundant in cancerous tissue and promotes tumor growth, invasion, carcinogenesis, and host–tumor interactions." (PMID 36430487, 2022). "Estimation of common cytokines like IL-6, TNF-α, and IL-1β in brain samples showed a rise in cytokine levels in CMF treated tumor-bearing animals." (PMID 35197512, 2022). "Specifically, IL-1β has been previously associated with promoting CRC, and findings have shown a role for IL-1β in interacting with immune cells and supporting tumor progression as well as invasiveness and resistance to certain chemotherapeutic agents." (PMID 36531053, 2022). "As to the pro-tumor ability, both IL-1β and IL-1α are found to contribute to tumor angiogenesis and invasiveness in the process of PCa progression." (PMID 36237303, 2022). "Although none of these selected factors, alone or in combination, induced osteoclasts from OPCs, IL-1α and IL-1β stimulated tumor-induced and RANKL-induced osteoclastogenesis." (PMID 36614130, 2022). "Inhibition of IL-1β slightly delayed primary tumor regrowth following paclitaxel treatment but increased spontaneous metastases." (PMID 35739593, 2022). "In conclusion, the current findings provide knowledge on the significant role of epigenetic actions of IL-1β on tumor progression, bone homing, and consequently bone metastasis formation." (PMID 36499741, 2022). "IL-1β encourages tumor cell growth by increasing blood flow from angiogenesis by activating vascular endothelial growth factors (VEGF)." (PMID 35892729, 2022). "For the first time, the correlation of salivary levels of TNF-α, IL-1β, and IL-6 with HER2 status, MCP-1, IL-1β, IL-2, and IL-4 with the hormonal status of the tumor was shown." (PMID 36286034, 2022). "Often a central player in tumor invasion and spread, IL-1β is also integral to the creation of an immunosuppressive network involving TAMs, Tregs, and MDSCs." (PMID 36031601, 2022). "In contrast, in a murine tumor model, IL-1β injection resulted in tumor regression, demonstrating that IL-1 can also have anti-tumor effects, for example, via induction of Th1/Th17 responses." (PMID 36293159, 2022). "Secondly, reducing IL1β in the bone inhibits expansion of the bone metastatic niche (osteoblasts, haematopoietic stem cells and endovascular cells), which results in tumour cells being held in this site, preventing proliferation into overt metastases." (PMID 36230739, 2022). "Both IL-1α and IL-1β were shown to exert a dual functions in promoting and suppressing tumor progression." (PMID 36237303, 2022). "Although an oversimplification, for charting purposes, the cytokines were split into three groups by their generalized tumor-destroying (IFN-γ, IL-2, and IL-5), tumor-promoting (IL-10 and IL-4), or SIRS-associated (IL-1β, IL-6, CXCL-1, and TNF-α) properties." (PMID 35465347, 2022). "Treating mice first with anti-IL-1β antibodies followed by anti-PD-1 antibodies completely abrogated tumor progression." (PMID 36074553, 2022). "Further studies are needed to confirm the molecular mechanisms that identify IL-1β-dependent TET-1 overexpression as a prerequisite for tumor progression and bone metastasis." (PMID 36499741, 2022). "In support of these findings, other studies showed that IL-1α or IL-1β levels are inversely correlated with ERα and/or PR levels in BCa tumor tissue from primary or regional metastasis." (PMID 35626710, 2022). "It was reported that proinflammatory cytokines TNF-α, IL-6, and IL-1β are crucial to immune response, inflammatory, and hematopoiesis, as well as development and progression of tumor." (PMID 35210942, 2022). "IL-10 can also induce tumor progression by inhibiting many cytokines such as IL-1a, IL-1b, IL-6, IL-8, IL-12, and IL-18." (PMID 35186043, 2022). "Surgical tumor resection can induce immunosuppressive activities by inducing pro-inflammatory and pro-tumorigenic cytokines such as IL-1β, IL-6, IL-10 CCL-2 and TGF-β, which recruit immunosuppressive cells such as MDSCs." (PMID 36611932, 2022).
tumor (continued). "The IL-1β expressed by tumor cells can significantly increase CXCL1 production in CAFs via paracrine signaling." (PMID 36275775, 2022). "Among the tumor-normal interface sections, three out of five sections showed the strongest correlation between IL1B-expressing macrophages and EMThigh RCC cells." (PMID 36423636, 2022). "We and others have previously shown in several different mouse models that the presence of a tumor leads to elevated serum levels of the pro-inflammatory cytokine IL1β." (PMID 36531986, 2022). "IL-1β also exerts anti-tumor effects, which can prevent metastatic cells from colonization in the metastatic place, thus inhibiting metastasis." (PMID 36237303, 2022). "The plasma concentration of proinflammatory cytokines, such as IL-1β, TNF-α, and IL-6, increases in several types of cancer due to the sustained inflammatory environment caused by the tumor and its stroma." (PMID 36072935, 2022). "In conjunction with GM-CSF and M-CSF, tumor-derived lactic acidosis in ovarian cancer was discovered to drive macrophage differentiation into a preinflammatory tumor phenotype (VEGFhigh CXCL8+ IL1β+)." (PMID 36311734, 2022). "Next, we ascertained if neutrophil-derived IL-1β was contributory to CAF-tumor cell IL-6/STAT-3 signaling." (PMID 36107485, 2022). "Various tumor-derived factors within or on TEVs surface induce MDSCs in vitro, including IL-1β, IL-6, IL-10, prostaglandin E2 (PGE2), TGF-β, stem cell factor (SCF), and VEGF." (PMID 36612080, 2022). "In this context, IL-1β, has also been shown to play an important role in tumor-mediated inflammation." (PMID 36712972, 2022). "IL-1β is abundant at tumor sites, and malignant and normal epithelial cells, as well as fibroblasts and immune cells, are all considered potential sources of IL-1β in different tumor models." (PMID 35471938, 2022). "For the criterion of tumor pathologic stage, our analyses showed that IL1B was downregulated in patients with stage I and II CESC compared with patients in stages III and IV (P < 0.05)." (PMID 36253777, 2022). "This assertion was further supported by the cytokine analysis, wherein we observed reduced IL1β expression in CD4+T cell obtained from tumor, lungs and peripheral blood." (PMID 35741331, 2022). "On one hand, they promote cancer growth and metastasis by instructing an immunosuppressive TME, mainly through IL-1β, and by stimulating the proliferation of tumor cells in autocrine and paracrine amplification loops." (PMID 35517498, 2022). "Conversely, the presence of IFN-γ and IL-1β is related to lower NO concentrations (critical in wound healing responses exploited by the tumour during disease progression)." (PMID 35406451, 2022). "IL-1β can promote tumor growth and metastasis by inducing the expression of various metastasis-related factors, such as matrix metalloproteinases (MMPs), vascular endothelial growth factor (VEGF), inflammatory chemokines and growth factor genes." (PMID 35513871, 2022). "When put on HFHCD, IL-1R1ΔLysM mice increased tumor size, despite impaired IL-1β signaling and decreased pro-IL-1β expression." (PMID 36104342, 2022). "We found significant correlations between periostin levels in tumor and VEGF-A, IFN-γ, IL-1β, and TNFα concentrations in tumor." (PMID 35056404, 2022). "In 2019, Zong and colleagues demonstrated that M1 macrophages induced the expression of the programmed death ligand 1 (PD-L1) in HCC cells through IL-1β, supporting the pro-tumor role of M1 macrophages and IL-1β." (PMID 36289606, 2022). "IL-1β is a major pleiotropic cytokine in tumor progression through effects on angiogenesis, proliferation, invasion, metastases, and myeloid-cell recruitment." (PMID 35382168, 2022). "Radiation- or tumor-cell-induced IL-1β has been shown to promote the metastatic characteristics of tumor cells." (PMID 36430236, 2022). "Proinflammatory cytokines produced by the tumor, such as IL-1a, IL-1b, IL-6, and TNF-α, can cross the blood–brain barrier (BBB) and migrate to the brain." (PMID 35736871, 2022).